MS4A3 (membrane spanning 4-domains A3)
Description:
Hematopoietic modulator for the G1-S cell cycle transition. Modulates the level of phosphorylation of cyclin-dependent kinase 2 (CDK2) through its direct binding to cyclin-dependent kinase inhibitor 3 (CDKN3/KAP).
Synonyms: HTm4; CD20L
Tractability: Antibody: its Gene Ontology location is reachable by antibodies, with high confidence; UniProt predicts a signal peptide or a membrane-spanning region.
Gene: Protein-coding gene on chromosome 11 (60,056,587 to 60,071,115, forward strand). Ensembl gene ENSG00000149516.
Subcellular location: Endomembrane system; Cytoplasm, perinuclear region
Subcellular location (Human Protein Atlas): Golgi apparatus
Pathways (Reactome):
Immune System: Neutrophil degranulation
Gene Ontology:
Molecular function: protein binding
Cellular component: plasma membrane; specific granule membrane; cytoplasm; endomembrane system; membrane; perinuclear region of cytoplasm
Genetic constraint (gnomAD): Loss-of-function variants: 13 observed, 17.97 expected, observed/expected ratio (o/e) 0.72, 90% interval 0.47 to 1.15. The upper end of that interval is the gene's LOEUF score, 1.15, which puts it in group 5 of 6, group 1 being the genes least tolerant of losing a copy. Missense variants: 233 observed, 219.13 expected, observed/expected ratio (o/e) 1.06, 90% interval 0.95 to 1.18. Synonymous variants: 71 observed, 87.25 expected, observed/expected ratio (o/e) 0.81, 90% interval 0.67 to 0.99.
Homologues: Orthologues: chimpanzee MS4A3 (93% identical), rabbit MS4A3 (69% identical), rat Ms4a3 (60% identical), mouse Ms4a3 (57% identical). Paralogues in human: MS4A18 (24% identical), MS4A4A (24% identical), MS4A2 (23% identical), MS4A6A (23% identical), MS4A12 (22% identical), MS4A15 (22% identical), MS4A8 (22% identical), MS4A7 (21% identical), MS4A14 (20% identical), MS4A5 (20% identical), MS4A1 (18% identical), MS4A10 (18% identical), and 4 more.
Diseases named in the same sentence as MS4A3 in open-access papers:
MS4A3 is named in the same sentence as 20 diseases in open-access papers, as found by Europe PMC text mining. Sharing a sentence is not in itself a finding about the gene and the disease. The quoted sentences say what the papers report.
myeloid leukemia (3 papers, 2015 to 2025). A clonal proliferation of myeloid cells and their precursors in the bone marrow, peripheral blood, and spleen. "MECOM isoform EVI1 has been reported to directly regulate gene transcription of MS4A3 in myeloid leukemia and of GATA2, regulating hematopoietic stem cell proliferation." (PMID 40664642, 2025).
Allergy (1 paper, 2015). An allergy is an immune response or reaction to substances that are usually not harmful. "We found that the levels of expression of genes involved in allergy development and innate immunity, including those encoding CLC, MS4A3, DEFA3, DEFA4, IL8RA, and IL8RB, were lower in PBMCs from IgG4-RD patients than from healthy controls." (PMID 25973893, 2015). "The expression of genes related to allergy or innate immunity, including CLC, MS4A3, DEFA3, DEFA4, IL8RA and IL8RB, was lower in PBMCs from patients with IgG4-RD than from healthy controls." (PMID 25973893, 2015).
anemia (1 paper, 2014). A reduction in the number of red blood cells, the amount of hemoglobin, and/or the volume of packed red blood cells. "The protein encoded by MS4A3 has been proposed to function as a hematopoietic cell cycle regulator, another potential link to the anemia observed in individuals with Vitamin B12 deficiency." (PMID 25147783, 2014).
breast carcinoma (1 paper, 2024). "Recent studies have revealed a close association between MS4A3 and tumorigenesis, with significant differences in MS4A3 expression observed in prostate cancer, ovarian cancer, and breast cancer tissues compared with normal tissues." (PMID 39717774, 2024).
gestational diabetes (1 paper, 2022). Carbohydrate intolerance first diagnosed during pregnancy. "Previously, we identified a lower DNA methylation degree at genomic sites near the genes ESM1, MS4A3, and TSPAN14 in the blood cells of adolescent offspring exposed to gestational diabetes and/or maternal obesity in utero." (PMID 35740266, 2022).
Obesity (1 paper, 2022). Accumulation of substantial excess body fat. "Based upon own previous findings in adolescent offspring of GDM women, we investigated the link between maternal diabetes and obesity in pregnancy, and the epigenetic reprogramming of ESM1, MS4A3, and TSPAN14 genes, in adult offspring blood cells and subcutaneous adipose tissue." (PMID 35740266, 2022).
Sepsis (1 paper, 2021). Sepsis is defined as life-threatening organ dysfunction caused by a dysregulated host response to infection. "Artificial intelligence systems identified eight out of twenty novel genetic markers (SDC4, CLEC5A, TCN1, MS4A3, HCAR3, OLAH, PLCB1, and NLRP1) that help predict sepsis severity or mortality." (PMID 33692779, 2021).
tumor (6 papers, 2015 to 2025). "For example, a recent study utilised the inducible Ms4a3-creERT2 lineage reporter to track the fate of monocytes following tumour entry over several weeks." (PMID 40523200, 2025). "This repression was mediated by direct binding of EVI1 to a proximal region in the MS4A3 promoter, and was necessary for the tumor promoting effects of EVI1 in a murine xenograft model." (PMID 25886616, 2015). "Experimental re-expression of MS4A3 in an EVI1 overexpressing cell line counteracted the tumor promoting effect of EVI1 in a murine xenograft model by increasing the rate of apoptosis." (PMID 25886616, 2015). "Immunohistochemical staining of tumor sections corroborated both the down-regulation of endogenous MS4A3 by EVI1 at the protein level, and the persistent expression of exogenous EVI1 and MS4A3 in the xenograft tumors." (PMID 25886616, 2015). "The overall percentage of TUNEL positive cells was significantly higher in U937_EVI1_MS4A3 tumors than in U937_EVI1_vec tumors, suggesting that re-expression of MS4A3 in EVI1-positive myeloid cells may slow tumor growth by enhancing the rate of cell death." (PMID 25886616, 2015). "The top three genes downregulated in the tumor-bearing group of male mice were Gm2058 (ubiquitin-conjugating enzyme E2H pseudogene, FC = 0.211, p < 0.05), Sst (somatostatin, FC = 0.313, p < 0.001), Ms4a3 (membrane-spanning 4-domains, subfamily A, member 3, FC = 0.327, p < 0.001)." (PMID 37573456, 2023). "Interestingly, MS4A3 did not slow the growth of EVI1-negative U937_vec tumors, suggesting either that endogenous MS4A3 was expressed at saturating levels in this cell line, or that MS4A3 specifically interfered with tumor growth on the background of the gene expression pattern evoked by EVI1." (PMID 25886616, 2015). "MS4A3 is a hematopoietic cell cycle regulator, and HEMGN plays an important role in hematopoietic development and neoplasms and is also involved in differentiation and proliferation." (PMID 27579896, 2016). "In summary, our data uncover MS4A3, a so far poorly studied gene, as a novel direct target of EVI1 in myeloid cells, and show that its repression plays a role in EVI1-mediated tumor aggressiveness." (PMID 25886616, 2015). "Our data reveal MS4A3 as a novel direct target of EVI1 in human myeloid cells, and show that its repression plays a role in EVI1 mediated tumor aggressiveness." (PMID 25886616, 2015).
cancer (2 papers, 2015 to 2021). A tumor composed of atypical neoplastic, often pleomorphic cells that invade other tissues. "MS4A3 (also known as HTm4) encodes a member of membrane-spanning 4-domains subfamily, which acts as an important cell cycle regulator in various cancers, especially in hematological malignancies." (PMID 26472107, 2015). "MS4A3, which was found to bind to two miRNAs in our ceRNA network, was shown in a previous study to be a target of EVI1, and its suppression has an important role in cancer." (PMID 33737947, 2021). "In addition to MYC, another two cancer-related molecules MYB and MS4A3 were also significantly down-regulated by all five shikonin derivatives." (PMID 26472107, 2015).
MS4A3 also shares sentences with these, for which no sentence is quoted: leukemia (2 papers); allergic rhinitis (1); COVID-19 (1); diffuse large B-cell lymphoma (1); hematological malignancies (1); infection (1); Neonatal sepsis (1); ovarian carcinoma (1); prostate carcinoma (1); type 1 diabetic (1); vitamin B12 deficiency (1).